INS (insulin)
Diseases named in the same sentence as INS in open-access papers (continued):
Sharing a sentence is not in itself a finding about the gene and the disease.
diabetes (continued). "The number of people using insulin pump therapy to manage their diabetes is growing rapidly." (PMID 21821504, 2009). "Similarly, non-insulin-dependent diabetes mellitus is characterized by pathological hyperglycemia in the presence of higher-than normal levels of plasma-insulin." (PMID 22505962, 2009). "This abnormality could be the earlier impairment of insulin sensitivity in the study population, since 70% of them had family history of diabetes." (PMID 19825145, 2009). "Whether or not this is so, the serotonin pathway provides an avenue for intervention in multiple forms of diabetes, since it directly influences the amount of insulin secreted." (PMID 20076734, 2009). "Common components of diabetes management include insulin and physical exercise." (PMID 20016800, 2009). "More recently, we showed that loss of HMGA1 expression, induced in mice by disrupting the HMGA1 gene, caused a type 2-like diabetic phenotype, in which, however, impaired glucose tolerance and overt diabetes coexisted with a condition of peripheral insulin hypersensitivity." (PMID 19460132, 2009). "For three instruments, different versions were developed: for the Self-Efficacy Score for Diabetes Scale (SED), the Maternal Self-Efficacy for Diabetes Management Scale and the Maternal Self-Efficacy for Diabetes Scale respectively, and the Insulin Management Diabetes Self-Efficacy Scale (IMDSES)." (PMID 19781095, 2009). "Intensive insulin therapy to maintain blood glucose levels as close to normal as possible has been shown from several studies to reduce micro- and macrovascular complications of diabetes." (PMID 18489577, 2008). "For example, a patient with diabetes may need numeracy to calculate their carbohydrate intake and adjust their insulin based on carbohydrates and/or current blood glucose level." (PMID 18452617, 2008). "Besides, to support the insulin therapy, several medical devicesconcerning diabetes are being developed." (PMID 18437199, 2008). "Refill compliance in type 2 diabetes mellitus: a predictor of switching to insulin therapy?" (PMID 17983433, 2008). "Some care recipients have diabetes that requires daily injections of insulin where it is essential that nursing staff have the knowledge to deal with any swings in blood sugar levels that may occur." (PMID 18816418, 2008). "Emerging evidence in animal studies suggests that direct drug effects on beta-cell function and insulin action could be involved as factors independent from changes in body composition in up to a quarter of treatment-related new onset diabetes." (PMID 18479520, 2008). "Continuing medical education programmes that focus on increasing primary care physician knowledge about the progression of diabetes, the physiological effects of insulin, and tools for successfully initiating insulin in patients with type 2 diabetes are needed." (PMID 18393965, 2008). "However, the role of insulin pulsatility in glucose metabolic control and diabetes is still not well understood." (PMID 18673579, 2008). "Diabetes has been recognized since about2000 B.C. However, until the discovery of insulin in 1921, diabetes was properlytreated so that the insulin-dependent diabetic could delay the emergence of thecomplications." (PMID 18437199, 2008). "ThusC-peptide may be an active peptide with relevant physiologic effects differentfrom and complementary to those of insulin.Several theories have been raised to explain C-peptide effects on renal function during diabetes." (PMID 18509500, 2008). "Approximately 5% of diabetics are classified as type-1 (insulin dependent DM), a condition characterized by abrupt onset at any age, destruction of pancreatic islet cells, and dependence on exogenous insulin." (PMID 20142943, 2008).
diabetes (continued). "The results of the United Kingdom Prospective Diabetes Study and the Diabetes, Insulin-Glucose, And Myocardial Infarction studies led Riddle to conclude that there is ‘compelling evidence’ that insulin treatment is not harmful with respect to cardiovascular disease and is most likely beneficial." (PMID 18393965, 2008). "Recent research suggests that earlier initiation of insulin is more physiologic and may be more effective in preventing complications of diabetes." (PMID 18279520, 2008). "It has been observed that defects in the G6PD gene correlate with diabetes and a more recent study proposed that alterations in genes controlling both insulin secretion and G6PD-mediated antioxidant defences may contribute to a predisposition to diabetes." (PMID 18485212, 2008). "Any effort to prolong endogenous insulin production may have a significant impact on the long-term quality of life for patients with Type 1 diabetes mellitus." (PMID 18167535, 2008). "Serum- and Glucocorticoid-inducible Kinase 1 (SGK1) is involved in the regulation of insulin secretion and may represent a candidate gene for the development of type 2 diabetes mellitus in humans." (PMID 18985156, 2008). "The Diabetes Attitude Wishes and Needs study, a large multinational survey of physicians and patients, indicated that US physicians were significantly more disposed to delay insulin therapy than physicians in most other countries." (PMID 18393965, 2008). "At present, the treatment of diabetes mainly involves a sustained reduction in hyperglycemia by the use of biguanides, thiazolidinediones, sulphonylureas, D-phenylalanine derivatives, meglitinides and α-glucosidase inhibitors in addition to insulin." (PMID 19330070, 2008). "Insulin and oral hypoglycemic agents are the major players in the management of the diabetes." (PMID 21593982, 2008). "Modern treatment of diabetes requires coherence with tailored insulin regimens including several daily insulin injections adapted to regular meals with certain content, daily self-care with repeated blood glucose measurements, and continuous learning about the treatment." (PMID 19040738, 2008). "However, some degree of controversy surrounds SMBG use, particularly with respect to the frequency of monitoring in non-insulin requiring diabetes." (PMID 19046192, 2008). "Exercise training has been known to be effective in type 2 diabetes mellitus by increasing insulin sensitivity, and regular exercise can strengthen antioxidant defenses and may reduce oxidative stress." (PMID 18477407, 2008). "Also, psyllium fiber significantly reduced post-prandial concentrations of serum triglycerides, glucose, and insulin in persons with diabetes suggesting a role for psyllium fiber in the management of diabetes." (PMID 18727833, 2008). "The blood glucose measurements are also important for the insulin-dependent diabetes therapies." (PMID 18437199, 2008). "Primary care physicians exhibited a clear dichotomy concerning whether adherence to a diabetes regimen or following physician's recommendations would prevent patients with type 2 diabetes from requiring insulin." (PMID 18393965, 2008). "Interestingly, the rs9402571 allele that associates with higher insulin secretion in TUEF and EUGENE2 accordingly associates with lower diabetes prevalence in the METSIM trial." (PMID 18985156, 2008). "Similarly, although the diabetes is severe and insulin requiring in both FCPD and type 1 diabetes (T1D), FCPD patients rarely develop ketoacidosis, in contrast to the T1D patients, who are ketosis prone." (PMID 18706099, 2008). "The AERx® Insulin Diabetes Management System (AERx® iDMS) delivers a liquid form of human insulin." (PMID 20046733, 2008). "Therefore, the objectives of the present study were to evaluate the KAP of diabetes mellitus among the type-1 diabetic patients receiving free monthly supplies of human insulin." (PMID 19902041, 2008).
diabetes (continued). "Both approaches could help patients with diabetes delay or even avoid the need for insulin injections." (PMID 18959471, 2008). "In patients with diabetes on insulin consideration should be given that they may be insulin resistant." (PMID 20108502, 2008). "On the other hand, type 2 diabetes mellitus (T2DM), distinguished by a deficient insulin secretion of varying degree and sometimes hyperinsulinemia with insulin resistance, is treated with oral hypoglycemic agents and/or insulin, depending on progress of the disease." (PMID 21264154, 2008). "In the Bergman model,the certain dynamics of the diabetes patient system can be represented asmathematical equations by employing three-order model: a glucose compartment, G, a remote insulin compartment, X, and an insulin compartment, I." (PMID 18566688, 2008). "Thus one goal of the insulin-dependent diabetes therapy is toprecisely capture the insulin-glucose dynamics of the normal person and design asystem yielding the insulin secretion quantitatively as close to the realmetabolism as possible." (PMID 18437199, 2008). "These modified hepatocytes were effective insulin-secreting bioimplants as evidenced by significant and durable correction of hyperglycemia and other metabolic abnormalities associated with diabetes, without evidence of tumor formation for at least 47 weeks." (PMID 18320053, 2008). "Thus, we consider it to be a strength that our population study targets a "normal" population, which in fact contain (at least) 18% insulin-resistant subjects and 4.2% with undiscovered diabetes mellitus." (PMID 18611252, 2008). "The rationale for inclusion of the RIAA/PAC tablet was based on results of in vitro screening studies employing insulin resistant 3T3-L1 adipocytes, db/db mouse diabetes studies, and a pilot clinical trial (unpublished results); all consistently showing improvement in insulin sensitivity." (PMID 18983673, 2008). "In a nested case-control study, AST, ALT, GGT as well as classic diabetes risk factors, insulin and C-reactive protein (CRP) were measured in 133 non-diabetic subjects at baseline of which 68 were cases and 65 were controls." (PMID 18533046, 2008). "Comparably to the lack of association with diabetes, no relation to insulin sensitivity (p = 0.7), insulin secretion (p = 0.8) or Disposition Index was found (p = 0.7)." (PMID 19052638, 2008). "A lack of insulin or insulin resistance, or defects in the insulin signaling pathways are the cause of metabolic diseases such as diabetes mellitus, which is characterized by hyperglycemia." (PMID 19330070, 2008). "Type 1 diabetes mellitus is characterized by an inability to produce insulin endogenously." (PMID 18167535, 2008). "In our cellular model, we have reproduced the conditions of postprandial hyperglycemia by shifting the glucose level from 5 to 20 mM and the conditions of insulin-resistant hyperglycemia (diabetes) by maintaining the cells "chronically" and stably at 20 mM glucose." (PMID 17555594, 2007). "Early introduction of insulin therapy can attain and maintain glucose targets when oral antidiabetic drug (OAD) regimens have failed to achieve glycemic goals, thereby reducing the risk of diabetes-related complications." (PMID 17448241, 2007). "VAT reduction and improved insulin action may not only be important for preventing or delaying diabetes, but also for modulating surrogate markers for cardiovascular disease and improving cardiovascular outcome." (PMID 17479164, 2007). "This is true even in insulin-resistant states such as diabetes." (PMID 17663761, 2007). "Lower insulin at follow-up in our GDM women who developed diabetes indicate more impaired β-cell function, which may have led to the early progression to diabetes." (PMID 17640759, 2007).
diabetes (continued). "We have shown that the lower proportion of South Asian patients with good diabetes control, and who are receiving insulin, is at least partly due to poorer standards of care in South Asians, although biological and cultural factors could also contribute." (PMID 17678547, 2007). "We found that pre-diabetes was associated with worsened levels of several major CVD risk factors as well as with increased carotid and femoral IMT independently of markers of adiposity (waist and BMI) or a marker of insulin resistance (insulin)." (PMID 17958881, 2007). "However, for effective diabetes management, further relevant data, including insulin doses and physical activity, are required." (PMID 18166525, 2007). "Compared with those who did not agree to storage, adjusted mean values for those who agreed to storage ranged from 9.7 percent lower for C-reactive protein to 8.7 percent higher for fasting insulin (among participants with diabetes), with most differences within ± 5 percent." (PMID 17822566, 2007). "GDM women who developed diabetes had lower gestational insulin area-under-the-curve (P = 0.05)." (PMID 17640759, 2007). "While most pancreas transplant recipients no longer require exogenous insulin for blood glucose control, the procedure has not been shown to decrease the severity or frequency of the secondary complications associated with diabetes." (PMID 17201925, 2007). "In children with diabetes, the result of such refractory glucose transport would be to inhibit critical developmental processes that are glucose-dependent, such as bone growth and insulin-dependent neuron growth, resulting in long term deficits." (PMID 19430606, 2007). "Unexpectedly, Fanconi-Bickel patients bearing GLUT2 invalidating mutations do not develop overt diabetes but their insulin secretions were not investigated." (PMID 18074013, 2007). "Studies, including those using sophisticated techniques of measuring insulin secretion have shown that first phase insulin secretion relative to insulin resistance during pregnancy is an important predictor of later development of diabetes in GDM women." (PMID 17640759, 2007). "Our findings indicate that amongst older women without diabetes and with fasting glucose levels in the normal range, fasting insulin is a stronger predictor of CHD and stroke risk than are fasting glucose or HbA1c." (PMID 17760500, 2007). "In people who don't have diabetes, the hormone insulin controls blood-sugar levels." (PMID 17760500, 2007). "Premixed insulin regimens are commonly used for type 2 diabetes mellitus (T2DM) patients." (PMID 17997807, 2007). "A number of prospective studies showed that higher levels of physical activity reduced the risk of type-2 diabetes and the beneficial effects of physical activity on the incidence of diabetes appear to be mainly due to the effect of muscular activity on insulin sensitivity." (PMID 17894855, 2007). "This patient also suffered from diabetes and dyslipemia and required daily injections of insulin." (PMID 17450213, 2007). "Questionnaires exist that assess perceptions of diabetes patients regarding insulin therapy." (PMID 17727695, 2007). "Because obesity is a risk factor for renal cell cancer, and diabetics are at higher risk than those without diabetes, it is possible that improved insulin sensitivity lowers renal cell cancer risk." (PMID 17653076, 2007). "Type 2 diabetes mellitus usually begins as insulin resistance and, as the need for insulin rises, the pancreas may lose its ability to produce insulin, thereby requiring exogenous insulin." (PMID 17371582, 2007). "Insulin is a therapeutic protein that is widely used for the treatment of diabetes." (PMID 18093308, 2007). "Furthermore, blood glucose must be monitored more frequently in patients with diabetes treated with insulin experiencing gastroparesis to prevent adverse hypoglycaemic episodes." (PMID 18093343, 2007).
diabetes (continued). "Transient protection against streptozotocin-induced diabetes has been observed possibly due to many GLUT2-mediated effects, including drug access to pancreatic ß cells, but not to accelerated urinary glucose loss or larger stores of pancreatic insulin." (PMID 18074013, 2007). "In this type of diabetes, the beta cell mass may be reduced but more importantly, there is an impaired ability to make and secrete insulin in response to a rise in glucose concentration." (PMID 16556307, 2006). "Type 2 Diabetes mellitus (T2DM) is a complex, multifactorial metabolic disease, characterized by high blood glucose level that results from deficiencies in insulin secretion, insulin action, or both." (PMID 17150099, 2006). "In addition to the potential for endocrine control of aging by insulin, signaling through insulin-like pathways is also a major factor in the development of cancer and diabetes, both of which have increased incidence at older ages." (PMID 16441841, 2006). "Although we recruited the subjects from primary care practices, some subjects may have been receiving their diabetes care from a specialist and would therefore be more likely to be using insulin." (PMID 16872541, 2006). "Thus, insulin treatment appeared to prevent some of the reduction in podocyte density accompanying STZ diabetes." (PMID 16539708, 2006). "The patient developed diabetes following his pancreatectomy and was started on insulin." (PMID 16942396, 2006). "In our patient, who had undergone a total pancreatectomy resulting in insulin deficiency and diabetes, the tumour was able to cause reversal of his diabetes and induce recurrent hypoglycaemia, even in the absence of any endogenous insulin secretion." (PMID 16942396, 2006). "Diabetes was treated with oral agents alone until age 40 when insulin was added." (PMID 16412238, 2006). "Considering that sympathetic over-activity is related to major cardiovascular accidents, early diagnosis and treatment of all insulin resistant patients should be considered, especially in patients with sympathetic over-activity and with I.F.G. and/or I.G.T nowadays called "pre-diabetes"." (PMID 16670002, 2006). "Implementing the RAPIA in these three Highly Indebted Poor Countries (HIPCs) was to see how a sustainable solution could be found to the issues of access to insulin and proper diabetes care under extreme conditions of scarce resources in the health sector." (PMID 16504123, 2006). "Therefore, impairment of insulin signal transduction results in attenuation of insulin action and leads to insulin resistance resulting in type 2 diabetes mellitus." (PMID 16729893, 2006). "Absolute or functional deficiencies of insulin or IGF-I may contribute to neuronal and vascular complications associated with diabetes." (PMID 15857517, 2005). "Roles in diabetes or hypoxia-induced insulin secretion are unstudied." (PMID 15730566, 2005). "Cognitive function may also seem to be affected in subjects with diabetes mellitus, given that cortical and subcortical structures responsible for this function are altered in some insulin-dependent patients." (PMID 16446918, 2005). "Low carbohydrate diet compares more favorably, at least over the short term, to traditional low fat for improving glycemic control, insulin sensitivity and dyslipidemia of diabetes with reduction in triglycerides, increase in HDL cholesterol and modification of LDL to less atherogenic form." (PMID 16018812, 2005). "Bezafibrate leads to considerable raising of HDL cholesterol and reduces triglycerides, improves insulin sensitivity and reduces blood glucose level, significantly lowering the incidence of cardiovascular events and new diabetes in patients with features of metabolic syndrome." (PMID 16168052, 2005). "In addition, as the transgenic mice were sacrificed 4 weeks after the onset of diabetes, this reduces the possibility of delayed destruction of the (pro)insulin expressing hepatocytes." (PMID 15679918, 2004).